FAM193B (family with sequence similarity 193 member B)
Synonyms: IRIZIO; KIAA1931; FLJ10404
Tractability: PROTAC: ubiquitination databases record sites on it; its protein half-life has been measured.
Gene: Protein-coding gene on chromosome 5 (177,519,788 to 177,554,586, reverse strand). Ensembl gene ENSG00000146067.
Subcellular location: Cytoplasm; Nucleus
Subcellular location (Human Protein Atlas): Nucleoli; Nucleoplasm
Gene Ontology:
Molecular function: protein binding
Cellular component: cytoplasm; nucleolus; nucleoplasm; nucleus
Genetic constraint (gnomAD): Loss-of-function variants: 27 observed, 55.68 expected, observed/expected ratio (o/e) 0.48, 90% interval 0.36 to 0.67. The upper end of that interval is the gene's LOEUF score, 0.67, which puts it in group 2 of 6, group 1 being the genes least tolerant of losing a copy. Missense variants: 1,022 observed, 970.95 expected, observed/expected ratio (o/e) 1.05, 90% interval 1 to 1.11. Synonymous variants: 448 observed, 385.58 expected, observed/expected ratio (o/e) 1.16, 90% interval 1.08 to 1.26.
Homologues: Orthologues: chimpanzee FAM193B (99% identical), macaque FAM193B (98% identical), pig FAM193B (92% identical), rabbit FAM193B (90% identical), rat Fam193b (86% identical), mouse Fam193b (85% identical), guinea pig FAM193B (77% identical), tropical clawed frog fam193b (48% identical), zebrafish fam193b (39% identical), Drosophila melanogaster CG7518 (19% identical). Paralogues in human: FAM193A (29% identical).
Diseases named in the same sentence as FAM193B in open-access papers:
FAM193B is named in the same sentence as 7 diseases in open-access papers, as found by Europe PMC text mining. Sharing a sentence is not in itself a finding about the gene and the disease. The quoted sentences say what the papers report.
alveolar rhabdomyosarcoma (1 paper, 2021). A rapidly growing malignant mesenchymal neoplasm. "FAM193B, also known as IRIZIO, has been found to cooperate with PAX3-FOXO1 fusion genes in alveolar rhabdomyosarcoma tumorigenesis." (PMID 34518442, 2021).
Obesity (1 paper, 2022). Accumulation of substantial excess body fat. "FAM193B has also been linked to pronounced sex differences in adiposity, which could be especially relevant when studying the relationship between reproduction and obesity among women." (PMID 35169479, 2022).
oculopharyngodistal myopathy (1 paper, 2024). Oculopharyngodistal myopathy (OPDM) is a rare, adult-onset hereditary muscle disease. "Interestingly, the FAM193B candidate was found in two affected siblings, both with oculopharyngodistal myopathy (OPDM)." (PMID 38297326, 2024).
neoplasm (2 papers, 2021 to 2022). A benign or malignant tissue growth resulting from uncontrolled cell proliferation. "We also elucidated its role in tumor development by sponging miR-328-3p (22 nucleotides long cancer related miRNA) and thereby upregulating the PI3K/AKT and MAPK/ERK signaling pathways via Family with sequence similarity 193 member B (FAM193B)." (PMID 34518442, 2021).
FAM193B also shares sentences with these, for which no sentence is quoted: Autoimmunity (1 paper); cancer (1); multiple sclerosis (1).